CST3 (cystatin C)
Diseases named in the same sentence as CST3 in open-access papers (continued):
Sharing a sentence is not in itself a finding about the gene and the disease.
hydronephrosis (5 papers, 2016 to 2024). Collection of urine in the renal pelvis that results in dilatation of the renal pelvis and calyces. "Multivariate logistic regression showed that only the serum cystatin C level was an independent risk factor for hydronephrosis." (PMID 32752030, 2020). "Though there are considerable limitations, there have been attempts made to evaluate cystatin C in patients with ON, which demonstrates a better performance than creatinine, as its increase is a better indicator of the severity of hydronephrosis." (PMID 33312728, 2020). "In another study, serum cystatin C levels increased in adults with ureteral calculi as hydronephrosis increased and differed significantly between patients with no and mild hydronephrosis, while SCr levels did not." (PMID 32752030, 2020). "This study shows that in children younger than 5 years old with hydronephrosis, GFR calculated on base of serum cystatin C level has strong statistical correlation with GFR calculated with Schwartz’s formula, however in infants under one year old this correlation seems to be less significant." (PMID 27069964, 2016).
kidney transplant (5 papers, 2020 to 2024). A surgical procedure in which one or both kidneys from a donor are implanted into a recipient. "This study compared the performance of serum creatinine (Cr) and cystatin C (CysC)-based GFR equations to measured GFR (mGFR) using iohexol among pediatric kidney transplant recipients." (PMID 38427073, 2024). "In conclusion, we discovered and validated urinary exosomal proteins LBP and CST3 as potent non-invasive biomarkers for ABMR in kidney transplant recipients." (PMID 36289608, 2022). "Particularly, we discovered and validated urinary exosomal proteins CST3 and LBP, which could be combined to serve as a potent composite biomarker of ABMR in kidney transplant recipients." (PMID 36289608, 2022).
liver fibrosis (5 papers, 2022 to 2026). "Recent studies have demonstrated that FIB-4, when combined with indices such as ALBI score and Creatinine-to-Cystatin C ratio, can enhance its predictive capability for liver fibrosis and liver failure." (PMID 41347130, 2025). "Serum cystatin C level was an indirect marker of liver fibrosis in several chronic liver diseases." (PMID 36466932, 2022). "Moreover, serum cystatin C has some advantages over the serum creatinine as a biomarker for eGFR, and it is elevated in early hepatic fibrosis rather than early kidney disease." (PMID 36466932, 2022).
Multiple Myeloma (5 papers, 2013 to 2025). "Microarray analysis had revealed that cystatin C was one of the most highly upregulated genes in multiple myeloma." (PMID 23986888, 2013). "The authors had shown that serum cystatin C was not only a sensitive marker of renal impairment, but also related to tumour burden and prognostic value in myeloma." (PMID 23986888, 2013). "The aim of this study was to compare the creatinine equations with cystatin C (CysC) equations to define renal impairment (RI) in newly diagnosed multiple myeloma (MM) patients and to analyse the equation that allows for identifying patients with more and worse prognostic factors." (PMID 35469191, 2022). "In contrast, serum NGAL was shown to be elevated in all stages of the myeloma spectrum (MGUS, smoldering MM (SMM), and MM), whereas serum cystatin C was increased in symptomatic MM patients." (PMID 32486490, 2020). "Several predictors (eGFR, M protein, and cystatin C) were identified for NGAL, which itself correlated with CKD according to kidney disease improving global outcomes (KDIGO) in MM patients and markers of myeloma burden." (PMID 32486490, 2020).
nephritis (5 papers, 2012 to 2023). Inflammation of renal tissue. "For patients with history of nephritis (n = 73 of whom 17 died), the results for cystatin C were similar; P = 0.001, RR 4.4 (95% CI 1.8 to 10.7)." (PMID 22390680, 2012). "Importantly, IgG anti-MDA levels were significantly elevated in SLE patients with active nephritis (p = 0.0005) and correlated with cystatin C estimated glomerular filtration rate and albuminuria." (PMID 29482604, 2018). "Among those without history of nephritis (n = 135 of whom 25 died cystatin C adjusted for age remained significant; P = 0.009, RR 4.6 (95% CI 1.5 to 14.5)." (PMID 22390680, 2012). "The fact that the nephritis manifestation in our study only influenced CVM to a modest degree, while cystatin C predicted mortality significantly both in patients with and without reported history of nephritis, further emphasizes the importance of cystatin C as a new useful biomarker." (PMID 22390680, 2012).
schizophrenia (5 papers, 2014 to 2025). A major psychotic disorder characterized by abnormalities in the perception or expression of reality. "A recent study investigated associations between peripheral blood biomarkers (including cystatin C) and symptom severity across MDD, BD, and schizophrenia." (PMID 40256164, 2025). "Recently, based on the result of a whole genome methylation analyze of schizophrenia patients, CST3 was considered to be important for neurodevelopment." (PMID 37633927, 2023).
vascular dementia (5 papers, 2012 to 2022). A degenerative vascular disorder affecting the brain. "The attempt to determine the association between CST3 polymorphism and AD or vascular dementia resulted in the associations between CST3 B genotype and AD patients older than 75, or vascular dementia patients younger than 75 years." (PMID 22783166, 2012). "Another study suggested that high serum CysC level increased the risk of vascular dementia, and detection of CysC and CST3 gene polymorphism may contribute to the early diagnosis of vascular dementia." (PMID 35148465, 2022). "Not only that, some molecules closely associated with inflammatory processes, such as serum homocysteine, uric acid, plasma cystatin C, and high-density lipoprotein are commonly regarded as the biomarkers of multiple system atrophy, AD, and vascular dementia." (PMID 28553204, 2017). "A synergistic association of CST3 and APOE ε4 alleles was observed in predicting vascular dementia patients." (PMID 22783166, 2012).
viral infection (5 papers, 2012 to 2026). "Cystatin C has also been found by others to respond to HIV and other viral infections." (PMID 22693552, 2012).
acute pancreatitis (4 papers, 2016 to 2025). An acute inflammatory process that leads to necrosis of the pancreatic parenchyma. "Our next aim was to elucidate the molecular mechanisms underlying our observation that under conditions of acute pancreatitis, CST3 lost its capacity to inhibit CTSB and CTSL-supporting disease progression." (PMID 39962054, 2025).
albuminuria (4 papers, 2012 to 2022). The presence of albumin in the urine, an indicator of KIDNEY DISEASES. "Albuminuria secondary to glomerular damage may have caused other functional markers to increase, such as cystatin C, due to competition for tubular uptake." (PMID 34549356, 2021). "Albuminuria and Cystatin C (CysC) are biomarkers of glomerular filtration and integrity in CRS and have a prognostic impact." (PMID 36498617, 2022). "Albuminuria and cystatin C (CysC) are the biomarkers of glomerular filtration and integrity in CRS." (PMID 36498617, 2022).
arterial disease (4 papers, 2012 to 2025). "Established arterial disease and Cystatin C were the strongest risk factors in all groups and were retained in the remaining analyses." (PMID 22390680, 2012). "Age, high cystatin C levels and established arterial disease were the strongest predictors for all- cause mortality." (PMID 22390680, 2012). "High cystatin C levels and arterial disease are strong predictors of overall mortality.Biomarkers like sVCAM-1, hsCRP, and aPL are significant predictors of CVM.Traditional risk factors, except smoking, are less impactful for CVM in SLE patients." (PMID 41179568, 2025). "Multivariable Cox regression model adjusted for age, arterial disease and cystatin C (208 patients)." (PMID 22390680, 2012). "The best multivariable model predicting CVM included age, established arterial disease, cystatin C and smoking (AICc value 77)." (PMID 22390680, 2012). "Established arterial disease, Cystatin C and inflammatory markers were strong predictors for both, but s-VCAM-1, a marker of endothelial cell activation, was only associated with CVM." (PMID 22390680, 2012).
Atrophy (4 papers, 2014 to 2024). Any weakening or degeneration, especially through lack of use. "Higher levels of Cystatin C (CysC) were positively associated with all three atrophy measures after adjusting for baseline brain volumes and t-tau and remained predictive of higher whole brain (P=0.009) and hippocampal atrophy (P=0.034) after adjusting for p-tau, age, ApoE status and sex." (PMID 25072324, 2014).
autoimmune disease (4 papers, 2022 to 2024). A disorder resulting from loss of function or tissue destruction of an organ or multiple organs, arising from humoral or cellular immune responses of the individual to their own tissue constituents. "Unsurprisingly for this autoimmune disease, invasive lymphocytes replaced PRR4+CST3+WFDC2− seromucous acinar cells nearly one-to-one." (PMID 38196575, 2024). "Cystatin C (Cys C), an endogenous inhibitor of CTSS activity, was found to be significantly reduced in the tears of SS patients compared to patients with other autoimmune diseases and non-autoimmune dry eye, which may contribute to the elevated CTSS activity seen in SS tears." (PMID 39408709, 2024).
diabetic neuropathy (4 papers, 2022 to 2025). A chronic, pathological complication associated with diabetes mellitus, where nerve damages are incurred due to diabetic microvascular injury involving small blood vessels that supply these nerves, resulting in peripheral and/or autonomic nerve dysfunction. "The relationship between the lifestyle behaviors and risk of diabetic neuropathy was mediated by cystatin C, GGT, total bilirubin, albumin, HDL-C, triglycerides, apolipoprotein A, CRP, and HbA1c with the proportion of mediation effect ranging from 3.22% to 11.35%." (PMID 36626356, 2023).
epilepsy (4 papers, 2010 to 2024). A brain disorder characterized by episodes of abnormally increased neuronal discharge resulting in transient episodes of sensory or motor neurological dysfunction, or psychic dysfunction. "Cystatin C (CysC) expression in the brain is elevated in human patients with epilepsy, in animal models of neurodegenerative conditions, and in response to injury, but whether up-regulated CysC expression is a manifestation of neurodegeneration or a cellular repair response is not understood." (PMID 20352108, 2010).
gout (4 papers, 2022 to 2026). A condition characterized by painful swelling of the joints, which is caused by deposition of urate crystals. "Cathepsin B and cystatin C play a pro-inflammatory role in gouty arthritis of the knee joint." (PMID 40584622, 2025).
hereditary amyloidosis (4 papers, 2012 to 2025). Hereditary amyloidosis refers to a group of inherited conditions that make up one of the subtypes of amyloidosis. "Hereditary amyloidosis cases, such as those associated with mutations in gelsolin, cystatin C, or lysozyme, typically occur in younger individuals or as part of familial syndromes." (PMID 40700073, 2025). "In fact the hereditary amyloidosis associated with cystatin C is caused by a point mutation at position 68 which is thought to weaken the interaction between the helix and the β-sheet." (PMID 23091450, 2012). "Hereditary amyloidosis refers to a wide spectrum of rare diseases with different causative mutations in the genes of various proteins including transthyretin, apolipoprotein AI and AII, gelsolin, lysozyme, cystatin C, fibrinogen Aα-chain, β2-microglobulin, apolipoprotein CII and CIII." (PMID 30665372, 2019).
HIV-1 infection (4 papers, 2011 to 2023). The type species of lentivirus and the etiologic agent of acquired immunodeficiency syndrome (AIDS). "For example, cathepsin B inhibition by cystatin C or CA-074Me (synthetic inhibitor) treatment resulted in enhancement of the CD4-independent HIV-1 infection in HeLa and TE671 cells." (PMID 31077130, 2019). "We analyzed intracellular expression of cystatin C in MDM after HIV-1 infection and found similar expression in infected and uninfected MDM." (PMID 22693552, 2012). "Levels of IL-6, sCD14 and sCD163 (both released by monocytes/macrophages), non-specific markers of inflammation (such as C-reactive protein and cystatin C), and markers of hypercoagulation and microbial translocation are variably increased during HIV-1 infection." (PMID 36672667, 2023). "The effect of HIV-1 infection on MDM expression of cathepsin B and its inhibitors, cystatin B and cystatin C, was assessed by Western blot and densitometry analysis." (PMID 22693552, 2012). "Because cystatin B is localized predominantly in the cytoplasm, while cystatin C is generally located in late endosomes or secreted, and because cystatin C did not affect the CD4-dependent HIV-1 infection in our study, the roles of cystatins B and C in HIV-1 infection should be different." (PMID 21541353, 2011).
Hypercholesterolemia (4 papers, 2016 to 2023). An increased concentration of cholesterol in the blood. "There was a significant association of B2M and cystatin C with hypercholesterolaemia (B2M: r = 0.065, p = .034; cystatin C: r = 0.115, p < .001)." (PMID 37155257, 2023).
hyperhomocysteinemia (4 papers, 2021 to 2025). A serious metabolic condition caused by mutations in the MTHFR gene, medications, or nutritional deficiency. "Alternatively, uremic toxins such as hyperhomocysteinemia, guanidine compound, and cystatin-C have a role in neurodegeneration." (PMID 33919810, 2021).
lung fibrosis (4 papers, 2016 to 2023). "Current data are in sharp contrast to previous analysis carried on human BALF from patients with idiopathic pulmonary fibrosis, for which the level of cathepsin B remained unchanged while cystatin C was significantly increased." (PMID 27658724, 2016). "Therefore, it is reasonable that CST3 ameliorates lung fibrosis by inhibiting cathepsins." (PMID 29724997, 2018). "We discovered two fibroblast-inhibiting cytokines, CST3 and GDF15, from normal epithelial cells and demonstrated their therapeutic effects in a bleomycin-induced pulmonary fibrosis mouse model." (PMID 29724997, 2018). "Collectively, recombinant CST3 and GDF15 could be developed as potential biopharmaceuticals for treating pulmonary fibrosis." (PMID 29724997, 2018). "Therefore, murine cystatin C is not a reliable marker of fibrosis during bleomycin-induced lung fibrosis." (PMID 27658724, 2016).
neuropathy (4 papers, 2015 to 2023). A disorder affecting the nervous system that manifests with pain, tingling, numbness, and/or muscle weakness. "High serum cystatin C levels have been previously associated with an increased risk of T2D, T2D-related neuropathy, and AD." (PMID 37342358, 2023).
Non-alcoholic Fatty Liver Disease (4 papers, 2021 to 2025). "The creatinine-to-cystatin C ratio (CCR) is an emerging marker of muscle mass, which influences the progression of nonalcoholic fatty liver disease (NAFLD)." (PMID 40529414, 2025).
non-small cell lung carcinoma (4 papers, 2015 to 2025). A group of at least three distinct histological types of lung cancer, including non-small cell squamous cell carcinoma, adenocarcinoma, and large cell carcinoma. "After FDR correction, associations remained significant between small cell lung cancer and creatinine, eGFR, cystatin C, glycated haemoglobin A1c, non-small cell lung cancer and albumin, lung squamous cell carcinoma and eGFR, creatinine, cystatin C. Lung adenocarcinoma and alkaline phosphatase." (PMID 39687887, 2024). "involving 664 non-small cell lung cancer patients found that creatinine/cystatin C ratio was associated with mortality in women, but not in men." (PMID 37409249, 2023). "For non-small cell lung cancer, a negative causal relationship was found with albumin (β=-0.024, P=0.002, FDR=0.016*), while a potentially positive causal relationship was observed with cystatin C (β=0.022, P=0.006, FDR=0.054)." (PMID 39687887, 2024).
Proteinuria (4 papers, 2018 to 2025). Increased levels of protein in the urine. "Association of eGFR, Proteinuria and Cystatin C Levels with R-DWIL and Total Burden of cSVD." (PMID 29930507, 2018). "Proteinuria and cystatin C are reliable predictors for the early detection of nephrotoxicity in acutely poisoned patients." (PMID 40361175, 2025).
pulmonary hypertension (4 papers, 2018 to 2024). Increased pressure within the pulmonary circulation due to lung or heart disorder. "Serological markers that have been correlated with pulmonary arterial hypertension comprise Cystatin C, endothelin, C-reaction protein, and inflammatory mediators." (PMID 39473890, 2024). "Prior investigations have proposed cystatin C as a predictive biomarker in pulmonary hypertension." (PMID 38752178, 2024).
abdominal aortic aneurysm (3 papers, 2012 to 2022). Enlargement and ballooning of the vessel that supplies arterial blood to the abdomen, pelvis and legs. "Human abdominal aortic aneurysm (AAA) lesions contain high levels of cathepsin S (CatS), but are deficient in its inhibitor, cystatin C. Whether plasma CatS and cystatin C levels are also altered in AAA patients remains unknown." (PMID 22844527, 2012).
aneurysm (3 papers, 2015 to 2021). Bulging or ballooning in an area of an artery secondary to arterial wall weakening. "The regular assessment of cystatin C was implemented as a potential marker for early detection in aneurysms because its reduction over time is associated with abdominal aneurysms." (PMID 25488804, 2015). "A reduction of cystatin C levels is thought to predict the formation of aneurysms and was therefore measured beginning with Part A cohort 3 onward." (PMID 25488804, 2015). "A sustained reduction in cystatin C levels that may have indicated the development of aneurysms was not apparent for any patient, whether dosed with monotherapy or in combination with lomustine." (PMID 25488804, 2015).
Anxiety (3 papers, 2014 to 2025). Intense feelings of nervousness, tension, or panic often arise in response to interpersonal stresses. "Cystatin C in the AS cohort was adversely related to the PGWB subdimensions anxiety, depressed mood, positive well-being, and vitality in women, but in men only to depressed mood (P < 0.006; R2 ≈ 6%)." (PMID 25219531, 2014). "In women in the AS cohort, cystatin C was significantly and adversely related to the dimensions anxiety, depressed mood, positive well-being, and vitality." (PMID 25219531, 2014). "Research indicates that over-reliance on biomarkers such as cystatin C may lead to overclassification of CKD, prompting unnecessary interventions and increasing patient anxiety." (PMID 40428218, 2025).
aortic stenosis (3 papers, 2016 to 2023). Aortic valve stenosis is a aortic valve disease caused by the incomplete opening of the aortic valve. "In a prospective study enrolling 68 consecutive patients with symptomatic severe aortic stenosis undergoing transfemoral or transapical TAVI, cystatin C levels in patients developing AKI were comparable to those with normal postoperative renal function within the first two postoperative days." (PMID 27609347, 2016). "This study included 390 consecutive patients with symptomatic severe aortic stenosis (AS) who underwent TAVI, and measured cystatin C-based eGFR at discharge." (PMID 37187794, 2023).